OTOF (otoferlin)
Description:
Key calcium ion sensor involved in the Ca(2+)-triggered synaptic vesicle-plasma membrane fusion and in the control of neurotransmitter release at these output synapses. Interacts in a calcium-dependent manner to the presynaptic SNARE proteins at ribbon synapses of cochlear inner hair cells (IHCs) to trigger exocytosis of neurotransmitter. Also essential to synaptic exocytosis in immature outer hair cells (OHCs). May also play a role within the recycling of endosomes (By similarity).
Synonyms: FER1L2; DFNB6; AUNB1; DFNB9; NSRD9
Tractability: Antibody: UniProt places it where antibodies can reach, with medium confidence; UniProt predicts a signal peptide or a membrane-spanning region; its Gene Ontology location is reachable by antibodies, with medium confidence. PROTAC: ubiquitination databases record sites on it.
Gene: Protein-coding gene on chromosome 2 (26,457,203 to 26,558,756, reverse strand). Ensembl gene ENSG00000115155.
Subcellular location: Cytoplasmic vesicle, secretory vesicle, synaptic vesicle membrane; Basolateral cell membrane; Endoplasmic reticulum membrane; Golgi apparatus membrane; Presynaptic cell membrane; Cell membrane; Golgi apparatus, trans-Golgi network
Pathways (Reactome):
Protein localization: Insertion of tail-anchored proteins into the endoplasmic reticulum membrane
Sensory Perception: Sensory processing of sound by inner hair cells of the cochlea
Gene Ontology:
Molecular function: calcium ion binding
Biological process: membrane fusion; regulation of neurotransmitter secretion; sensory perception of sound; synaptic vesicle exocytosis
Cellular component: trans-Golgi network; basolateral plasma membrane; cytosol; endoplasmic reticulum membrane; Golgi membrane; membrane; plasma membrane; presynaptic membrane; synaptic vesicle membrane; Golgi apparatus
Genetic constraint (gnomAD): Loss-of-function variants: 212 observed, 233.68 expected, observed/expected ratio (o/e) 0.91, 90% interval 0.81 to 1.02. The upper end of that interval is the gene's LOEUF score, 1.02, which puts it in group 4 of 6, group 1 being the genes least tolerant of losing a copy. Missense variants: 2,564 observed, 2,723.1 expected, observed/expected ratio (o/e) 0.94, 90% interval 0.91 to 0.97. Synonymous variants: 1,035 observed, 1,088.2 expected, observed/expected ratio (o/e) 0.95, 90% interval 0.9 to 1.
Gene-disease validity (ClinGen):
ClinGen rates the evidence that OTOF causes each of these diseases.
autosomal recessive nonsyndromic hearing loss 9 (autosomal recessive): Definitive.
Homologues: Orthologues: chimpanzee OTOF (99% identical), macaque OTOF (99% identical), dog OTOF (96% identical), rat Otof (95% identical), pig OTOF (95% identical), mouse Otof (95% identical), guinea pig OTOF (91% identical), rabbit OTOF (88% identical), tropical clawed frog otof (78% identical), zebrafish otofa (76% identical), zebrafish otofb (68% identical), Drosophila melanogaster mfr (21% identical). Paralogues in human: FER1L6 (46% identical), DYSF (34% identical), MYOF (32% identical), FER1L5 (27% identical).
Diseases named in the same sentence as OTOF in open-access papers:
OTOF is named in the same sentence as 51 diseases in open-access papers, as found by Europe PMC text mining. Sharing a sentence is not in itself a finding about the gene and the disease. The quoted sentences say what the papers report.
deafness (81 papers, 2010 to 2026). An inherited or acquired condition characterized by the complete loss of the ability to hear from one or both ears. "Progress in understanding the structure and function of otoferlin is urgently needed, given that its defects cause deafness in humans with hundreds of missense mutations that have remained hard if not impossible to interpret." (PMID 41091875, 2025). "Otoferlin, a multirole Ca2+ signaling protein normally associated with deafness, is also unique to the malignant cells and one of the most highly expressed of the residual disease and recurrence signature genes." (PMID 40723261, 2025). "OTOF-related auditory neuropathy: Biallelic OTOF mutations disrupt synaptic vesicle release in inner hair cells, accounting for 3%–10% of prelingual deafness." (PMID 41181184, 2025). "More than 200 human pathogenic and likely pathogenic mutations in OTOF have been linked to the nonsyndromic autosomal recessive deafness DFNB9 or mild to moderate hearing impairment." (PMID 41091875, 2025). "Mouse mutagenesis targeting C2G Ca2+ binding (OtofDDA, p.D1836/1837A in mouse, and p.D1841/1842A in human) revealed deafness due to a complete loss of IHC exocytosis despite substantial (~60%) basolateral otoferlin levels." (PMID 41091875, 2025). "These first in human trials of gene replacement therapy are focusing on deafness arising from mutations in the OTOF gene." (PMID 38528140, 2024). "Currently, most of the treatments for deafness caused by OTOF mutations use physical methods such as cochlear implants, and there are no clinically available drugs." (PMID 38014592, 2024). "Of the patients included in this study, subjects with profound deafness had inactivating mutations in both OTOF alleles, whereas mild phenotypes correlate with the presence of at least one missense variant or one in-frame deletion." (PMID 37677959, 2024). "OTOF mutations lead to autosomal recessive non-syndromic prelingual deafness DFNB9 or hearing impairment that can be temperature sensitive." (PMID 38195526, 2024). "DFNB9 is a form of hereditary deafness characterized by a well‐defined mechanism in which mutations in the OTOF gene result in auditory nerve conduction disorder, ultimately leading to deafness." (PMID 39556694, 2024). "Interest in otoferlin began with the discovery of mutations in the OTOF gene that were identified as responsible for recessive profound deafness in humans." (PMID 37538852, 2023). "Mutations of otoferlin cause autosomal recessive deafness in humans, and genetic inactivation of the otoferlin gene impairs Ca2+-dependent exocytosis in mouse auditory inner hair cells and causes profound deafness." (PMID 37998383, 2023). "Remarkably, some otoferlin mutations, notably in the C2F domain, can lead to exacerbated deafness when body temperature rises during a fever." (PMID 37538852, 2023). "MYO15A and OTOF were among the first genes identified to be associated with deafness using conventional approaches." (PMID 37189200, 2023). "OTOF deficiency causes nonsyndromic prelingual deafness in humans, and OTOF-deficient mice are profoundly deaf." (PMID 35862790, 2022). "Most patients with NSAN caused by OTOF variants present with severe prelingual or profound deafness; however, the phenotypes of TSAN patients reported in this and previous studies did not follow this pattern." (PMID 34692690, 2021). "Analysis of the influence of ω-3 fatty acids on DNA methylation: Biological functions and diseases related to early development include neurosensory nonsyndromic recessive deafness caused by OTOF mutations, Lissencephaly and Nervous system development." (PMID 34828297, 2021). "By virtue of being one of the first deafness genes identified, OTOF has been tested in molecular genetic diagnostic settings for over two decades, allowing an estimate of the global burden of OTOF-associated hearing loss." (PMID 33256196, 2020).
deafness (continued). "Among six ferlins, dysferlin and otoferlin mutations cause genetic diseases in humans: muscular dystrophy and deafness, respectively." (PMID 33182221, 2020). "Mutations in dysferlin and otoferlin genes cause heredity diseases: muscular dystrophy and deafness in humans, respectively." (PMID 33182221, 2020). "The present report shows the efficient generation of the first large animal model with OTOF null mutations, which would be useful for the understanding of otoferlin function and human deafness." (PMID 32265471, 2020). "Nevertheless, the loss of otoferlin function in humans has a distinct disease phenotype and causes nonsyndromic sensorineuronal deafness DFNB9 affecting SV exocytosis by the cochlear IHCs." (PMID 32106631, 2020). "There is one human deafness locus in the Cos15 region of CFA17, namely DFNB9, a deafness locus caused by a recessive mutation in the gene Otoferlin (OTOF)." (PMID 32413090, 2020). "Different mutations of the OTOF gene, encoding for otoferlin protein expressed in the cochlear inner hair cells, induces a form of deafness that is the major cause of nonsyndromic recessive auditory neuropathy spectrum disorder in humans." (PMID 32265471, 2020). "We have previously determined that expression of exogenous otoferlin rescues the deafness and balance defects associated with endogenous otoferlin depletion." (PMID 31582816, 2019). "Mutations in otoferlin result in deafness and depending on the species, mild to strong vestibular deficits." (PMID 31582816, 2019). "Mutation in OTOF encoding otoferlin leads to a nonsyndromic deafness named autosomal recessive deafness 9 (DFNB9)." (PMID 29760588, 2018). "OTOF is a transmembrane protein required for calcium-dependent synaptic exocytosis in cochlear sensory cells and mutations in OTOF cause deafness." (PMID 29973527, 2018). "Rab 8b has been recognized as a binding partner of otoferlin, a member of the ferlin family transmembrane anchored proteins whose mutations cause nonsyndromic deafness due to defective neurotransmission." (PMID 29760588, 2018). "Mutations of the otoferlin encoding gene are among the most frequent causes of inherited profound deafness in humans." (PMID 29111973, 2017). "Within this region is the deafness locus for DFNB9, a non-syndromic deafness locus caused by a recessive mutation in the gene Otoferlin (OTOF, OMIM entry 603681)." (PMID 26664958, 2015). "It is assumed that OTOF mutations accounted for deafness in at least 7, and possibly 16, of the 160 patients (4.4-10.0%)." (PMID 24053799, 2013). "OTOF mutations are thus a frequent cause in the Japanese deafness population and mutation screening should be considered regardless of the presence/absence of OAEs." (PMID 24053799, 2013). "OTOF mutations are a frequent cause in the Japanese deafness population and mutation screening should be considered regardless of the presence/absence of OAEs." (PMID 24053799, 2013). "Mutations in OTOFERLIN (OTOF) lead to the autosomal recessive deafness 9 (DFNB9)." (PMID 38189623, 2024). "OTOF codes for the hair cell synaptic protein otoferlin and mutations cause autosomal recessive HI ranging from mild threshold increases (some with temperature-dependent worsening) to deafness." (PMID 38528140, 2024). "In clinical otology and audiology, we may occasionally see a patient with a very “focal” lesion accounting for their hearing loss, for example, the monogenic COCH mutation of DFNA9 deafness or the many otoferlin mutations of DFNB9 deafness." (PMID 37425006, 2023). "According to the HGMD database, about 89.0% of the variants in CDH23 gene, 85.0% of the variants in TECTA gene, and 69.4% of the variants in OTOF gene are missense mutations, which reminds us that the missense mutations in deafness causative genes should be given more consideration." (PMID 36597107, 2023). "Deficiency of otoferlin causes profound prelingual deafness in humans and animal models." (PMID 34335185, 2021).
deafness (continued). "In addition to an expanded understanding of the types of variants in otoferlin that cause deafness, the structure and function of otoferlin have been extensively characterized through functional studies that have greatly informed experimental therapies." (PMID 33256196, 2020). "In the present study we selected Japanese subjects that had hereditary hearing loss without GJB2 mutations, mitochondrial mutations, enlarged vestibular aqueduct or auditory neuropathy-associated OTOF mutations, and we aimed to detect the spectrum of rare deafness genes in these patients." (PMID 24164807, 2013). "Knowing that deafness, either due to biallelic variants in OTOF or auditory neuropathies/synaptopathies of other etiologies, cannot be reliably diagnosed with OAE screenings, but could be aided with currently available therapies, requires switching newborn hearing screenings to routine ABR testing." (PMID 33256196, 2020). "Therefore, we propose that gene delivery mediated by dual‐AAV vectors might be suitable to treat deafness forms caused by mutations in large genes such as OTOF." (PMID 30509897, 2019). "Regarding hearing-specific variables, later-onset deafness, a shorter duration of deafness, and identifiable etiologies (notably specific genetic mutations such as GJB2 and OTOF) exert significant influence." (PMID 41682664, 2026). "D1837 (along with D1836) was substituted by alanine in OtofDDA mice that showed reduced (~60%) basolateral otoferlin levels in IHC, abolished IHC exocytosis, and deafness." (PMID 41091875, 2025). "We present a structure-function analysis of otoferlin, a deafness gene product, for which the first gene replacement therapy of the inner ear is currently in clinical trials." (PMID 41091875, 2025). "In Taiwan, common deafness-associated genes include GJB2, SLC26A4, OTOF, MYO15A, and MTRNR1, which were similar to those found in other populations." (PMID 40943139, 2025). "OTOF had been found to be associated with neuronal transmission function, and in a mouse model with complete knockout of the OTOF gene, it was found that the auditory phenotype exhibited extremely severe deafness." (PMID 40718794, 2025). "Expanding screening via next-generation sequencing (NGS) to include other established (e.g., MYO15A, OTOF, CDH23, TMC1) and emerging deafness genes would significantly enhance diagnostic yield and capture a broader spectrum of genetic causes." (PMID 41181184, 2025). "In Taiwan, the common deafness-associated genes assessed, in order of prevalence included GJB2, SLC26A4, OTOF, MYO15A, and MT-RNR1." (PMID 38840095, 2024). "Otoferlin knockout mice have profound deafness due to a failure of neurotransmitter release at the IHC synapse and are likely to be an appropriate animal model for DFNB9.257, 258 In these mice, exocytosis triggered by Ca2+ in IHCs is almost abolished." (PMID 39442262, 2024). "This dual AAV strategy can stably and persistently express full‐length OTOF and restore hearing to wild‐type levels in adult OTOFp.Q939*/Q939* mice with profound deafness." (PMID 38014592, 2024). "Given the role of otoferlin in hair cell exocytosis, the deafness of OtofDDA/DDA mice most likely reflects a synaptopathy, which we further investigated by patch-clamp recordings from IHCs." (PMID 38152587, 2023). "Among the novel transcripts in deafness-related gene loci, we found that otoferlin, one of the key ribbon synapse proteins, expressed a short transcript originating from an unannotated exon 6b." (PMID 37248244, 2023). "The Slc17a8–/– and Otoferlin–/– mice exhibit profound deafness because both vGlut3 and Otoferlin are heavily involved in the packaging and exocytosis of ribbon synapse vesicles containing the excitatory neurotransmitter glutamate in the IHCs, respectively." (PMID 36687561, 2022).
deafness (continued). "Another study reported for the first time the generation of otoferlin (OTOF) gene disrupted sheep, which provided a model allowing better understanding and development of new therapies for human deafness related to genetic disorders." (PMID 35656550, 2022). "Genetic causes, particularly pathogenic variants in several highly prevalent deafness genes (e.g., SLC26A4, GJB2, MYO15A and OTOF) are associated with favorable CI outcomes, whereas certain imaging findings such as CND are associated with unfavorable outcomes." (PMID 36009393, 2022). "Dual-AAV6 vectors allowed otoferlin overexpression in 19–30% of inner HCs of deaf Otof-/- mice and improved the deafness." (PMID 36340687, 2022). "Pathogenic variants in most deafness genes, including GJB2, SLC26A4, OTOF, MTRNR1, COCH, and MYH9, have been associated with favorable outcomes, probably because the pathology is confined to the inner ear." (PMID 36009393, 2022). "The causative variants in deafness genes were confirmed, namely eight with bi-allelic GJB2 variants, one with bi-allelic SLC26A4 variants, and one with bi-allelic OTOF variants." (PMID 34943631, 2021). "For both deafness genes, mouse models are available: CaV1.3 knock-out (KO) mice and otoferlin KO mice." (PMID 33036242, 2020). "Mutations in LOXHD1, OTOF, PCDH15, TBL1X, and TMC2 have been associated with hereditary disorders of balance, deafness or hearing loss in humans (NCBI gene db and GeneCards)." (PMID 32770228, 2020). "All seven of these families have variants in seven different known deafness genes, LRTOMT, LHFPL5, TMPRSS3, OTOF, MYO15A, ESRRB, and KCNE1." (PMID 31835641, 2019). "In contrast to many other deafness or Usher genes, otoferlin seems dispensable for auditory hair cell (HC) development." (PMID 30509897, 2019). "This proof‐of‐concept study demonstrates that split viral vectors are suitable to partially restore hearing in otoferlin knock‐out mice and, therefore, present a major step towards clinical gene therapy applications for this deafness form." (PMID 30509897, 2019). "Common deafness-associated genes in Taiwanese families, in order of prevalence, included GJB2, SLC26A4, OTOF, MYO15A, and MTRNR1, which are similar to those found in other populations." (PMID 31581539, 2019). "Common deafness-associated genes in the Taiwanese patients assessed, in the order of prevalence, included GJB2, SLC26A4, OTOF, MYO15A, and MTRNR1, which were similar to those found in other populations." (PMID 31581539, 2019). "In HEK 293 cells otoferlin, a protein involved in human autosomal recessive deafness, is co-localized and co-expressed with Rab8 contributing with trans-Golgi trafficking." (PMID 29760588, 2018). "In our series, as in most of published studies, prior to comprehensive genetic testing, patients were prescreened for common deafness mutations (in our cohort, GJB2/GJB6, OTOF and MT-RNR1, selected for their high prevalence in Spain)." (PMID 29986705, 2018). "Another important presynaptic player is otoferlin, coded by a deafness gene, which assumes a multi-faceted role in vesicular exocytosis and, when disrupted, causes auditory synaptopathy." (PMID 27635230, 2016). "It is interesting to note that the RAI1 gene is absent in the candidate gene list for genes associated with nonsyndromic and syndromic HL whereas OTOF and SLC26A4 are known as deafness-related genes." (PMID 27082237, 2016). "For example, in hereditary deafness with mutations of specific genes, such as, GJB2, SLC26A4, OTOF, COCH, and MYH9, mitochondrial mutations, CI is expected to provide successful results." (PMID 25373420, 2014). "Remarkably, proof‐of‐concept has been established in mouse models of DFNB9, a congenital form of deafness caused by OTOF mutations, and clinical trials for DFNB9 gene therapy have already confirmed the therapeutic potential of this approach for genetic forms of human hearing loss." (PMID 41508981, 2026).